IL12A (interleukin 12A)
Diseases named in the same sentence as IL12A in open-access papers (continued):
Sharing a sentence is not in itself a finding about the gene and the disease.
IL12A also shares sentences with these, for which no sentence is quoted: liver cancer (3 papers); adenoma (2); allergic asthma (2); Allergy (2); Behçet Disease (2); breast carcinoma (2); depression (2); hepatocellular carcinoma (2); immune diseases (2); inflammatory bowel disease (2); Sjögren’s syndrome (2); systemic lupus erythematosus (2); ulcerative colitis (2); abscess (1); ankylosing spondylitis (1); Childhood Asthma (1); chronic hepatitis B (1); chronic obstructive pulmonary disease (1); colon adenocarcinoma (1); colon carcinoma (1); colorectal (1); cyst (1); dermatitis (1); differentiated thyroid carcinoma (1); endothelial dysfunction (1); Familial adenomatous polyposis (1); fungal infection (1); Glioblastoma Multiforme (1); heart failure (1); Hematologic cancer (1).
A further 27 diseases each share a sentence with IL12A in 1 paper.